ZBTB26 (zinc finger and BTB domain containing 26)
Description:
May be involved in transcriptional regulation.
Synonyms: ZNF481; bioref
Tractability: PROTAC: UniProt records ubiquitination sites on it.
Gene: Protein-coding gene on chromosome 9 (122,915,566 to 122,931,565, reverse strand). Ensembl gene ENSG00000171448.
Subcellular location: Nucleus
Gene Ontology:
Molecular function: identical protein binding; protein binding; sequence-specific double-stranded DNA binding; DNA-binding transcription repressor activity, RNA polymerase II-specific; RNA polymerase II cis-regulatory region sequence-specific DNA binding; DNA binding
Biological process: negative regulation of transcription by RNA polymerase II; regulation of cytokine production; regulation of immune system process
Cellular component: nucleoplasm; nucleus
Genetic constraint (gnomAD): Loss-of-function variants: 12 observed, 33.2 expected, observed/expected ratio (o/e) 0.36, 90% interval 0.23 to 0.59. The upper end of that interval is the gene's LOEUF score, 0.59, which puts it in group 2 of 6, group 1 being the genes least tolerant of losing a copy. Missense variants: 311 observed, 552.01 expected, observed/expected ratio (o/e) 0.56, 90% interval 0.51 to 0.62. Synonymous variants: 155 observed, 194.57 expected, observed/expected ratio (o/e) 0.8, 90% interval 0.7 to 0.91.
Homologues: Orthologues: chimpanzee ZBTB26 (100% identical), rabbit ZBTB26 (99% identical), pig ZBTB26 (99% identical), guinea pig ZBTB26 (99% identical), macaque ZBTB26 (97% identical), rat Zbtb26 (96% identical), mouse Zbtb26 (96% identical), tropical clawed frog zbtb26 (66% identical), zebrafish zbtb26 (54% identical). Paralogues in human: ZBTB6 (42% identical), ZBTB12 (30% identical), BCL6 (22% identical), ZBTB46 (19% identical), BCL6B (18% identical), ZBTB14 (17% identical), ZBTB49 (16% identical), ZBTB21 (16% identical), ZBTB33 (15% identical), NACC2 (15% identical), NACC1 (14% identical), ZBTB7B (14% identical), and 16 more.
Diseases named in the same sentence as ZBTB26 in open-access papers:
ZBTB26 is named in the same sentence as 9 diseases in open-access papers, as found by Europe PMC text mining. Sharing a sentence is not in itself a finding about the gene and the disease. The quoted sentences say what the papers report.
thyroid dysgenesis (2 papers, 2021 to 2025). "An additional cohort screening of 156 individuals with congenital thyroid dysgenesis identified two additional ZBTB26 gene variants of unknown significance." (PMID 34946811, 2021).
congenital hypothyroidism (1 paper, 2021). A thyroid hormone deficiency present from birth. "Two further ZBTB26 gene variants were identified in a cohort of 156 individuals with congenital hypothyroidism." (PMID 34946811, 2021). "In summary, 2 out of 156 individuals with congenital hypothyroidism presented a risk variant of unknown functional significance in the ZBTB26 gene." (PMID 34946811, 2021).
ZBTB26 also shares sentences with these, for which no sentence is quoted: atherosclerosis (1 paper); breast carcinoma (1); cancer (1); hypothyroidism (1); Primary hypothyroidism (1); thyroid carcinoma (1); type 2 diabetes (1).